NSUN7 (NOP2/Sun RNA methyltransferase family member 7)
Diseases named in the same sentence as NSUN7 in open-access papers:
NSUN7 is named in the same sentence as 35 diseases in open-access papers, as found by Europe PMC text mining. Sharing a sentence is not in itself a finding about the gene and the disease. The quoted sentences say what the papers report.
male infertility (8 papers, 2021 to 2025). The inability of the male to effect fertilization of an ovum after a specified period of unprotected intercourse. "In humans, NSUN7 activity is required for proper flagella movement and sperm motility, and mutations result in male infertility." (PMID 41252183, 2025). "Beyond oncology, NSUN7 has been strongly associated with male infertility, although the precise mechanisms underlying its contribution remain poorly understood." (PMID 41516134, 2025). "Mutations in the testis-specific RNA methyltransferase NSUN7 are associated with defective fibrous sheath, impaired sperm motility, and male infertility." (PMID 41516134, 2025). "NSUN7 encodes a methyltransferase protein by the same name and has been implicated in familial restrictive cardiomyopathy as well as male infertility through the mechanism of sperm dysmotility." (PMID 35990004, 2022). "Mutations in NSUN7 have been observed to contribute to male infertility in humans and mice." (PMID 41516134, 2025). "NSUN7 installs m5C in eRNA, and loss-of-function mutation of NSUN7 has been associated with male infertility, implicating that the NSUN7-regulated m5C methylation pathway may serve as an essential balancer in germ cell differentiation." (PMID 34272618, 2021). "Moreover, mutations in NSUN7 are associated with male infertility, suggesting that NSUN7 may play distinctive roles that remain unknown." (PMID 39574165, 2024). "This indicates that NSUN7 is a critical regulator of spermiogenesis, and its malfunction is a contributing factor to male infertility." (PMID 41516134, 2025). "The dysfunction of NSUN7 has been reported to result in male infertility, and NSUN7 is downregulated in prostate cancer compared with normal prostate tissue, acting as a protective factor in patients with prostate cancer." (PMID 36911744, 2023). "NSUN7, a member of the NSUN methyltransferase family, reduces protein activity and motility of sperms and is associated with male infertility." (PMID 37701433, 2023).
glioma (7 papers, 2020 to 2023). A benign or malignant brain and spinal cord tumor that arises from glial cells (astrocytes, oligodendrocytes, ependymal cells). "High expression of NSUN7 is associated with shortened survival in low-grade gliomas." (PMID 36855207, 2023). "Our data confirmed the up-regulation of ANG, EXO1, FBXO17, IGF2BP3, and NSUN7 in glioma than normal samples (all p < 0.0001)." (PMID 33634155, 2021). "The results showed that ANG, EXO1, FBXO17, IGF2BP3, and NSUN7 displayed distinctly higher expression levels in glioma compared to controls (p < 0.05)." (PMID 33634155, 2021). "All five RNA:m5C methyltransferase genes, NOP2, NSUN4, NSUN5, NSUN6, and NSUN7, were differentially expressed between normal brain tissues, low grade and high grade glioma tissues." (PMID 32974125, 2020). "Future research will be needed to functionally dissect the role that NSUN7 plays in glioma, as well as to decipher why its expression levels are highly predictive of patient survival." (PMID 32375858, 2020). "We obtained six genes associated with prognosis (P < 0.01), among which NOP2, NSUN2, NSUN4, NSUN5, and NSUN7 acted as risk factors (HR > 1), and NSUN6 played a protective role (HR < 1) in gliomas." (PMID 32974125, 2020). "According to a recent study on gliomas, five genes related to m5C methyltransferase were identified to construct a risk signature (5MM) and were used to predict glioma prognosis, including NOP2, NSUN4, NSUN5, NSUN6 and NSUN7." (PMID 36637205, 2023). "The expression of NOP2, NSUN2, NSUN4, NSUN5, and NSUN7 were positively correlated in gliomas." (PMID 32974125, 2020). "After validation by RT-qPCR, IGF2BP3, NSUN7, EXO1, and FBXO17 had higher expression levels in glioma than controls." (PMID 33634155, 2021). "The results showed that NSUN4, NSUN7, DNMT1, DNMT3B, DNMT3A, NOP2 and NSUN5 were negatively correlated with the overall survival of low‐grade glioma, while NSUN6 was positively correlated with the overall survival." (PMID 33400376, 2021). "Through survival analysis, this study constructed a low‐grade glioma prognostic model with 4 genes (NSUN4, NSUN7, DNMT1 and NSUN6) and drew a nomogram accordingly." (PMID 33400376, 2021). "Our data suggested that IGF2BP3, NSUN7, EXO1, and FBXO17 were highly expressed in AC-, MES-, NPC-, and OPC-like malignant cells, which could be related to poor prognosis for glioma patients." (PMID 33634155, 2021).
Sepsis (4 papers, 2023 to 2025). Sepsis is defined as life-threatening organ dysfunction caused by a dysregulated host response to infection. "An increase in the mean precursor strength of plasma protein polypeptides, such as NSUN7, is associated with sepsis." (PMID 36855207, 2023). "NOP2 and NSUN7 were upregulated in the peripheral blood mononuclear cells (PBMCs) of sepsis patients [areas under the ROC curve (AUC) = 0.707 and 0.828, respectively], indicating that NSUN7 may act as new potential diagnostic biomarkers and therapeutic targets." (PMID 41462962, 2025). "However, whether NSUN7 is associated with sepsis caused by SARS-CoV-2 remains unclear." (PMID 38600309, 2024). "Overall, NSUN7, NOP2, PUS1, PUS3, and FTO were identified as important diagnostic markers for sepsis." (PMID 37701433, 2023). "To predict the occurrence of sepsis, we constructed a nomogram model for diagnosing sepsis based on the expression levels of five hub RMGs (NSUN7, FTO, NOP2, PUS1 and PUS3)." (PMID 37701433, 2023). "Finally, by using machine learning, we identified five hub RMGs (NSUN7, FTO, NOP2, PUS1, and PUS3), which showed efficient diagnostic value of sepsis." (PMID 37701433, 2023). "Meanwhile, our results found NSUN7 displayed a negative correlation with monocytes, activated NK cells and CD8 T cells, but a positive correlation with neutrophils, γδT cells and M1 macrophages, suggesting that NSUN7 may be related to the excessive inflammatory response in sepsis." (PMID 37701433, 2023). "NSUN7 has been systematically studied in male sperm motility, but its mechanism of action in tumours and sepsis has not been elucidated." (PMID 36855207, 2023). "Firstly, we determined the genes expression in PBMCs by qRT-PCR analysis, and found the expression of NSUN7, NOP2, PUS1 and PUS3 in septic patients (septic shock and sepsis) at day 1 were significantly higher than in healthy volunteers, and FTO expression was lower in septic patients." (PMID 37701433, 2023). "In addition, we identified that five RMGs (NSUN7, NOP2, PUS1, PUS3 and FTO) could function as biomarkers for clinic diagnose of sepsis." (PMID 37701433, 2023).
liver cancer (3 papers, 2020 to 2024). An epithelial or non-epithelial malignant neoplasm that arises from the liver. "For a model, we used SNU-423, a liver cancer cell line, which displays hypermethylation-associated silencing of the NSUN7 promoter." (PMID 37173708, 2023). "Notably, high expression of almost all m5C regulators was significantly associated with shorter OS in HCC patients except NSUN7, indicating that dysregulation of m5C regulators may strongly influence liver cancer patient survival." (PMID 33365328, 2020). "An additional link between DNA methylation and transcriptional silencing was established using the DNA demethylating agent 5-aza-2′-deoxycytidine, that restored NSUN7 expression in the hypermethylated liver cancer cell lines." (PMID 37173708, 2023). "We have also shown that the addition of the m5C modification in CCDC9B mRNA stabilizes the molecule, whereas the NSUN7 mediated epigenetic inactivation in liver cancer decreases CCDC9B mRNA half-life." (PMID 37173708, 2023). "Overall, all these data indicate that NSUN7 catalyzes the 5-methylcytosine methylation of the CCDC9B mRNA and that NSUN7 epigenetic inactivation induces the loss of these RNA modifications in liver cancer cells." (PMID 37173708, 2023). "The 5-methylcytosine RNA methyltransferase NSUN7 undergoes epigenetic inactivation in liver cancer that prevents correct mRNA methylation." (PMID 37173708, 2023). "In liver cancer, NSUN7 is epigenetically inactivated, which prevents correct mRNA methylation." (PMID 38468490, 2024). "Most importantly, proteomic analyses determined that CCDC9B loss impaired protein levels of its partner, the MYC-regulator Influenza Virus NS1A Binding Protein (IVNS1ABP), creating sensitivity to bromodomain inhibitors in liver cancer cells exhibiting NSUN7 epigenetic silencing." (PMID 37173708, 2023). "However, NSUN7 promoter CpG island was methylated among different cancer types, being the three most often targeted sites in melanoma (35 of 47, 74.5%), liver cancer (11 of 18, 61.1%) and hematological malignancies (77 of 137, 56.2%)." (PMID 37173708, 2023). "We carried out the bisulfite genomic sequencing of multiple clones in the liver cancer cell lines HEP3B2-1-7, SNU-475, SNU-387, SNU-423, SNU-398 and HUH-7 utilizing primers that encompassed the NSUN7 transcription start site located in the 5’-end CpG island." (PMID 37173708, 2023).
Alzheimer disease (2 papers, 2023 to 2024). A progressive, neurodegenerative disease characterized by loss of function and death of nerve cells in several areas of the brain leading to loss of cognitive function such as memory and language. "We found that NSUN7, SLC6A8, CXCL1 and LCN8 were significantly different in groups B compared to A, and SLC1A3 and LCN8 were significantly different in groups C compared to A. NSUN7, a m5C RNA methyltransferase gene, is differentially expressed in Alzheimer's disease patients." (PMID 39185136, 2024).
glioblastoma (2 papers, 2020 to 2025). The most malignant astrocytic tumor (WHO grade IV). "Mechanistically, NSUN7 deposits m5C on circular RNAs (circRNAs), stabilizing these transcripts, enhancing the expression of stemness markers, and sustaining self-renewal in glioblastoma stem-like cells." (PMID 41148823, 2025). "For instance, NSUN7 is highly expressed in glioblastoma and correlates with poor prognosis." (PMID 41148823, 2025). "We also studied the expression of RNA:m5C methyltransferases in glioblastomas (GBM) stratified by IDH mutant status, and findings indicated that NSUN5, NSUN6, and NSUN7 were still differentially expressed." (PMID 32974125, 2020).
Infertility (2 papers, 2020 to 2024). "Recently, there have been several reports on the relationship between NSUN7 mutation and infertility." (PMID 39340806, 2024). "Depletion of NSUN7 or ADAD1 are known to cause infertility, suggesting that RMPs that are selectively expressed in meiotic stages of spermatogenesis are essential for proper sperm formation and/or maturation." (PMID 32375858, 2020). "The chemically induced mutation of Ste5Jcs1 in Nsun7 induced defects in the motility of sperm and infertility in male mice; however, the molecular mechanism of this phenotype remains unclear." (PMID 39340806, 2024). "Sperm motility defects and infertility have been observed in male mice with a mutation in Nsun7." (PMID 39340806, 2024).
prostate carcinoma (2 papers, 2023). A carcinoma that arises from epithelial cells of the prostate gland. "NSUN7 may also serve as a pivotal biomarker for predicting biochemical recurrence in patients with prostate cancer." (PMID 36855207, 2023).
bipolar disorder (1 paper, 2023). A disorder of the brain that causes unusual shifts in mood, energy, activity levels and the ability to carry out day-to-day tasks. "NSUN7 may also be associated with psychiatric disorders, including schizophrenia, bipolar disorder, and major depressive disorders." (PMID 36855207, 2023).
breast carcinoma (1 paper, 2022). "The result demonstrated that most of these m5C regulators, except NSUN2, NSUN7, and DNMT2, were overexpressed in breast cancer." (PMID 35812757, 2022).
colorectal tumour (1 paper, 2024). "There were no obvious differences in NSUN6, NSUN7 and TRDMT1 expression between the colorectal tumour tissues and adjacent normal tissues." (PMID 38468490, 2024).
COVID-19 (1 paper, 2024). A disease caused by infection with severe acute respiratory syndrome coronavirus 2. "In addition, we used multiple machine learning methods to screen for five risk genes (KLF5, NSUN7, APH1B, GRB10 and CD4), which are used to predict COVID-19 severity." (PMID 38600309, 2024).
Ewing sarcoma (1 paper, 2023). A small round cell tumor that lacks morphologic, immunohistochemical, and electron microscopic evidence of neuroectodermal differentiation. "The overall survival in Ewing sarcoma is significantly associated with NSUN7 immunoreactivity, an independent favourable prognostic marker." (PMID 36855207, 2023).
head and neck squamous cell carcinoma (1 paper, 2021). A squamous cell carcinoma that arises from any of the following anatomic sites: lip and oral cavity, nasal cavity, paranasal sinuses, pharynx, larynx, and salivary glands. "NSUN4, NSUN5, NSUN6 and NSUN7 are associated with cancer development in HCC, head and neck squamous cell carcinoma (HNSCC), pancreatic cancer and glioma 29, 114-116." (PMID 34512153, 2021).
hepatocellular carcinoma (1 paper, 2023). A malignant tumor that arises from hepatocytes. "Low mRNA levels of NSUN7 in both hepatocellular cancer cohorts were also associated with lower expression of CCDC9B." (PMID 37173708, 2023). "All normal liver tissues from the TCGA cohort were unmethylated at NSUN7, and the NSUN7 expression levels were similar to those observed in the unmethylated cases of liver carcinoma." (PMID 37173708, 2023).
lung carcinoma (1 paper, 2025). "Recently, a seven-gene m6A/m5C risk model, comprising METTL3, NPLOC4, RBM15, YTHDF1, IGF2BP1, NSUN3, and NSUN7, was developed to stratify the prognosis of early-stage lung cancer." (PMID 40279954, 2025).
Neonatal sepsis (1 paper, 2023). Systemic inflammatory response to infection in newborn babies. "A recent study has reported that NSUN7 is up-regulated in neonatal sepsis, combined with bioinformatic analyses, NSUN7 is closely related to immune and inflammatory responses, implying its potential as a biomarker for the pathogenesis of neonatal sepsis." (PMID 37701433, 2023).
pancreatic cancer (1 paper, 2022). "In addition, NSUN6, NSUN7, and DNMT3B exhibited downregulated trends in pancreatic cancer." (PMID 35864471, 2022).
rectal cancer (1 paper, 2023). A primary or metastatic malignant neoplasm that affects the rectum. "Therefore, to further substantiate the results of the bioinformatics analysis, TMAs from patients with rectal cancer were immunohistochemically stained for NSUN4, NSUN7, and DNMT1." (PMID 36911744, 2023).
sarcoma (1 paper, 2023). A usually aggressive malignant neoplasm of the soft tissue or bone. "NSUN2 and NSUN7 were positively correlated with DDR1 expression in BLCA, HNSC, LIHC, sarcoma (SARC), THCA, and thymoma (THYM)." (PMID 37031216, 2023).
vascular tumor (1 paper, 2023). "The low levels of NSUN7 were only associated with shorter survival in the non-vascular tumor type [65.4% of the cases (log-rank P = 0.021; HR = 1.852, 95% CI = 1.089–3.149] among the examined clinicopathological characteristics." (PMID 37173708, 2023).
tumor (13 papers, 2020 to 2024). "Interestingly, some of the common down-regulated genes, such as EPHA7 and NSUN7, are known for both their tumor suppressing and promoting roles, or are associated with overall survival (OS) (SLC22A31), while others have clear pro-tumorigenic roles (ADGRF1, LOX, LY6G5C, SNAI2, TNFRSF11B, ZNF233)." (PMID 36769365, 2023). "Herein, we have demonstrated that a previously poorly characterized m5C RNA methyltransferase, NSUN7, undergoes cancer-specific epigenetic transcriptional silencing in different tumor types." (PMID 37173708, 2023). "The level of NSUN3 and NSUN6 was increased in tumor samples, whereas the level of ALYREF, NSUN5, and NSUN7 was decreased in tumor samples." (PMID 33365328, 2020). "Next, we detected the protein expression levels of NSUN4, NSUN7, and DNMT1 via IHC staining in a tissue microarray containing 80 paired normal and tumor tissues." (PMID 36911744, 2023). "Among the differentially expressed genes present, DNMT1, NSUN2, NSUN4, and TET2 were highly expressed in LNM + tumor tissues while NSUN5 and NSUN7 expression was reduced." (PMID 37907576, 2023). "Regulators with amplificated CNV tended to highly expressed in tumor samples (e.g., DNMT1, ALYREF, and NSUN5), and vice versa (e.g., NSUN7 and NSUN6)." (PMID 36389669, 2022). "In contrast, the expressions of NSUN3, NSUN4, NSUN7, TRDMT1, DNMT1, YBX1, and TET2 were low in tumors and had a tumor-suppressive effect." (PMID 36661693, 2022). "The expression of ALKBH1 (p = 0.036), ALYREF (p < 0.001), NOP2 (p < 0.001), NSUN2 (p < 0.001), NSUN4 (p < 0.001), NSUN5 (p < 0.001), NSUN6 (p < 0.001), NSUN7 (p = 0.006), and YBX1(p < 0.001) were significantly upregulated in tumor tissues compared with the adjacent mucosa." (PMID 35281843, 2022). "Most m5C regulators showed tumor-promoting effects, except for TET2 and NSUN7." (PMID 34957065, 2021). "The results revealed significant elevation of NSUN7 and DNMT1 in normal tissues compared with tumor tissues, while NSUN4 showed no obvious difference between the two groups." (PMID 36911744, 2023).
cancer (8 papers, 2020 to 2025). A tumor composed of atypical neoplastic, often pleomorphic cells that invade other tissues. "Data-mining of the available expression profiles of the cancer cell lines showed that NSUN7 methylation was associated with RNA downregulation." (PMID 37173708, 2023). "Analyses of the TCGA RNA-sequencing data validated the in vitro cancer cell lines results, showing that in the primary liver tumors NSUN7 hypermethylation was also associated with low-levels of the transcript (Student t-test, P < 0.001)." (PMID 37173708, 2023). "The methyltransferase NSUN7 is primarily recognized for its role in cancer, where it methylates the mRNA of CCDC9B (Coiled-Coil Domain Containing 9B) and reduces MYC expression." (PMID 41516134, 2025). "Future experiments should test if the overexpression of CUBN and NSUN7 generates a radiation resistance phenotype and perhaps even a cancer resistance phenotype in cell lines and mice." (PMID 40001939, 2025). "Among all the RMP-cancer pairs studied, we identified NSUN7 as the top-ranked RMP in terms of prediction of lower-grade glioma (LGG) patient survival (p = 8e− 24), although its biological role still remains uncharacterized." (PMID 32375858, 2020). "In this risk score signature, four genes (NOP2, NSUN4, NSUN5, and NSUN7) were cancer-promoting and NSUN6 was a cancer-suppressor gene." (PMID 32974125, 2020). "Notably, NSUN7 has the least foundational research on cancer progression with only two studies, whereas NSUN2 has been the most extensively studied." (PMID 41462962, 2025). "This family of epigenetic drugs is intensively assessed in ongoing cancer clinical trials and those liver tumors harboring NSUN7 epigenetic inactivation might constitute an unexpected niche of patients where these compounds could possess efficacy." (PMID 37173708, 2023). "Existing basic experiments indicate that NOP1, NSUN2, NSUN3, and NSUN4 predominantly promote the majority of cancers, while NSUN5, NSUN6, and NSUN7 demonstrate context-dependent effects—promoting some cancers but inhibiting others." (PMID 41462962, 2025).
NSUN7 also shares sentences with these, for which no sentence is quoted: brain injury (1 paper); colon cancer (1); familial restrictive cardiomyopathy (1); hematological malignancies (1); infection (1); major depressive disorder (1); mastitis (1); melanoma (1); psychiatric disorder (1); schizophrenia (1); septic shock (1); thymoma (1).